DORIP1 (dopamine receptor interacting protein 1)
Description:
Could be a regulator of the dopamine receptor signaling pathway.
Synonyms: C14orf28; DRIP1; DRIP-1; c14_5270
Tractability: No criterion of Open Targets' tractability assessment is met for any kind of drug.
Gene: Protein-coding gene on chromosome 14 (44,897,200 to 44,907,257, forward strand). Ensembl gene ENSG00000179476.
Subcellular location (Human Protein Atlas): Cytosol
Genetic constraint (gnomAD): Loss-of-function variants: 30 observed, 28.14 expected, observed/expected ratio (o/e) 1.07, 90% interval 0.8 to 1.45. The upper end of that interval is the gene's LOEUF score, 1.45, which puts it in group 5 of 6, group 1 being the genes least tolerant of losing a copy. Missense variants: 314 observed, 312.89 expected, observed/expected ratio (o/e) 1, 90% interval 0.91 to 1.1. Synonymous variants: 127 observed, 108.51 expected, observed/expected ratio (o/e) 1.17, 90% interval 1.01 to 1.36.
Homologues: Orthologues: chimpanzee C14H14orf28 (99% identical), macaque C7H14orf28 (99% identical), dog DORIP1 (98% identical), pig DORIP1 (98% identical), rat C6h14orf28 (97% identical), guinea pig DORIP1 (97% identical), mouse Gm527 (96% identical), zebrafish DORIP1 (51% identical).
Diseases named in the same sentence as DORIP1 in open-access papers:
DORIP1 is named in the same sentence as 5 diseases in open-access papers, as found by Europe PMC text mining. Sharing a sentence is not in itself a finding about the gene and the disease.
DORIP1 shares sentences with these, for which no sentence is quoted: type 1 diabetes (2 papers); cancer (1); colorectal cancer (1); schizophrenia (1); tumor (1).